CA9 (carbonic anhydrase 9)
Diseases named in the same sentence as CA9 in open-access papers (continued):
Sharing a sentence is not in itself a finding about the gene and the disease.
esophageal squamous cell carcinoma (4 papers, 2015 to 2023). Esophageal squamous cell carcinoma (ESCC) is a type of esophageal carcinoma (EC) that can affect any part of the esophagus, but is usually located in the upper or middle third. "Second, we examined the association of CA9 high expression with the clinicopathologic characteristics of esophageal squamous cell carcinoma and esophageal adenocarcinoma." (PMID 26156831, 2015). "PADI4 also promotes tumorigenesis and metastasis in esophageal squamous cell carcinoma by upregulating carbonic anhydrase 9 (CA9) expression." (PMID 37804426, 2023). "A few studies reported that CA9 was highly expressed in esophageal adenocarcinoma and esophageal squamous cell carcinoma." (PMID 26156831, 2015). "In our study, the rate of high CA9 expression was very high in esophageal adenocarcinoma (90 %) and precancerous lesions (74 %–94 %) but was very low in esophageal squamous cell carcinoma (9 %)." (PMID 26156831, 2015). "Several studies showed high CA9 expression in esophageal squamous cell carcinoma, ranging from 41 to 100 %." (PMID 26156831, 2015). "In esophageal squamous cell carcinoma (ESCC), PADI4 can stimulate the growth of ESCC cells and upregulate CA9 to promote ESCC metastasis." (PMID 37020554, 2023).
gastric adenocarcinoma (4 papers, 2008 to 2025). "It has been reported that CA9 expression is an independent prognostic marker in oesophageal and gastric adenocarcinomas, but the relationship between prognosis and CA9 expression in oesophageal squamous cell carcinoma (ESCC) remains controversial." (PMID 18841153, 2008).
Hodgkins lymphoma (4 papers, 2019 to 2024). A heterogeneous group of malignant lymphoid neoplasms of B-cell origin characterized histologically by the presence of Hodgkin and Reed-Sternberg (HRS) cells in the vast majority of cases. "A Hodgkin’s lymphoma cell line (HDLM-2) endogenously expressing CA9 can activate Syk-dependent CLEC2 signaling, providing enticing evidence for a novel function of CA9 in hematological cancers." (PMID 39768175, 2024). "We demonstrated that Hodgkin lymphoma cells, which endogenously express CA9, but not PDPN, induce CLEC2 signaling." (PMID 39768175, 2024). "Altered platelet biology, a negative prognostic factor in advanced Hodgkin lymphoma, may be influenced by CA9-mediated activation of platelets or megakaryocytes." (PMID 39768175, 2024).
leukemia (4 papers, 2012 to 2022). A malignant (clonal) hematologic disorder, involving hematopoietic stem cells and characterized by the presence of primitive or atypical myeloid or lymphoid cells in the bone marrow and the blood. "Despite these promising results, further immunohistochemistry staining for detecting CA9 in leukaemia samples is recommended." (PMID 36415514, 2022). "The current study suggested that the changes in CA9 gene expression level might be used as a predictive marker to assess early prognosis at the time of detection of de novo leukemia, and then monitor tumor progress during treatment." (PMID 36415514, 2022). "In specific types of leukaemia, CA9 is up-regulated, which may control neo-angiogenic pathways." (PMID 36415514, 2022). "To explore the direct role of leukemia cell derived IFN-γ in immune evasion, we used CRISPR/Ca9 to create IFNG KO clones in the BBC2 cells and generated two complete KO clones that are confirmed at both the protein (above) and genomic DNA (below) levels." (PMID 34906138, 2021).
meningioma (4 papers, 2013 to 2024). A generally slow growing tumor attached to the dura mater. "Our studies on several meningioma cell lines cultured in hypoxic conditions validated the association of CA9 and PD-L1 expression." (PMID 32839486, 2020). "We also demonstrated the prognostic significance of CA9 expression alone in outcome of meningiomas and also when it was co-expressed with PD-L1 to predict the risk for tumor recurrence in our cohort." (PMID 32839486, 2020). "We then evaluated the expression of specific candidate proteins: NFKB2, pSTAT3, RELB, and CA9 by immunohistochemistry based on availability of the unstained slides and we correlated their expression with that of PD-L1 in our meningioma cohort." (PMID 32839486, 2020). "We observed high expression of NFKB2, RELB, pSTAT3, and positive CA9 expression in 30% (26/88), 26% (24/91), 63% (46/73), and 51% (37/72) of the meningioma cases, respectively." (PMID 32839486, 2020). "Interestingly, we detected a heterogeneous pattern of hypoxia in almost half of the meningioma cases; highlighted by membranous CA9 positivity." (PMID 32839486, 2020). "Also, among low grade meningiomas, CA9 expression tended to be more common in recurrent tumors." (PMID 23877362, 2013). "Similarly, we also categorized the meningioma cases in to 4 subgroups based on CA9 expression (positive/negative) and PD-L1 expression into high and low (median = 0.08%)." (PMID 32839486, 2020). "CA9 displayed both membranous and cytoplasmic expression and highlighted the hypoxic areas in meningioma; patchy in tumor cells that were not directly adjacent to any large vascular channels and also in viable cells around the necrotic areas in anaplastic meningiomas." (PMID 32839486, 2020). "We then categorized the meningiomas cases based on co-expression of all three markers: PD-L1 (high/low, median = 0.08%), NFKB2 (high/low), and CA9 (positive/negative) into 8 subgroups." (PMID 32839486, 2020).
metastatic cancers (4 papers, 2016 to 2025). A carcinoma which has spread from the original site of growth to another anatomic site. "CA9 is a powerful marker used to diagnose various types of metastatic cancers, including cervical, renal, breast and head and neck tumors." (PMID 27478411, 2016).
Obesity (4 papers, 2021 to 2024). Accumulation of substantial excess body fat. "qRT-PCR analysis further confirmed the lower expression of CA3 in obesity, while CA9 expression was substantially similar in VAT and limited in SAT, independently from the metabolic conditions." (PMID 36646964, 2023). "In conclusion, the expression of major transporters, such as GLUT1, MCT1, and MCT4, involved in the metabolism of glucose and lactate, as well as the hypoxic marker CA9, was not altered by obesity in the models under study, even though tumors of HFD-fed mice showed lesser vascularization." (PMID 35158830, 2022).
prostate adenocarcinoma (4 papers, 2014 to 2025). "In both TMAs, CA9 staining was significantly stronger in NEPC compared to primary adeno-PCa and adeno-CRPC, indicating that NEPC is more hypoxic than prostate adenocarcinoma." (PMID 30655535, 2019).
thyroid cancer (4 papers, 2020 to 2025). "In thyroid cancer, chronic hypoxia within the tumor stimulates the production of hypoxia-inducing factors, thereby regulating key genes such as vascular endothelial growth factor, GLUT-1 (glucose transporter 1), P21, and carbonic anhydrase 9 to jointly promote tumor growth, invasion, and metastasis." (PMID 40166062, 2025).
tongue squamous cell carcinoma (4 papers, 2015 to 2022). A squamous cell carcinoma that arises from the tongue. "However, the role of CA9 in the molecular mechanisms of tongue squamous cell carcinoma (TSCC) pathogenesis remains unclear." (PMID 32299152, 2020).
anemia (3 papers, 2016 to 2024). A reduction in the number of red blood cells, the amount of hemoglobin, and/or the volume of packed red blood cells. "In this experimental setting, anemia treatment induced more expressions of SPINK1 mRNA and SPINK1 protein in tumor tissues according to the extent of tumor hypoxia, monitored as the CA9 mRNA levels (R2 = 0.6301 and R2 = 0.4449, respectively)." (PMID 34747365, 2021).
carcinoma in situ (3 papers, 2013 to 2026). "We also examined dysadherin and CA9 expression in carcinoma in situ and in metastatic CRC, including both primary tumors and liver metastases." (PMID 41535258, 2026).
cervical tumor (3 papers, 2014 to 2017). "Glut1, on the other hand, is also a HIF-1α target gene induced under hypoxia and its expression has been shown to correlate significantly with CA9 in cervix tumors from patients." (PMID 27901496, 2017). "Depending on the tumor analysed, the level of colocalization between CA9 and pimonidazole in cervix tumors varies, with some levels of non-overlap even when the colocalization is excellent." (PMID 27901496, 2017).
Cirrhosis (3 papers, 2018 to 2025). A chronic disorder of the liver in which liver tissue becomes scarred and is partially replaced by regenerative nodules and fibrotic tissue resulting in loss of liver function. "As patients with advanced cirrhosis stages had higher serum CA9 concentrations, we evaluated the prognostic value of CA9 in these patients with the cut-off of 400 pg/ml according to the median level." (PMID 30011326, 2018). "The CA9 levels in different stages of cirrhosis differed significantly between Child A, B and C patients, with the highest levels found in Child C stage patients (Child A median 252 pg/ml, Child B 490 pg/ml and Child C 833 pg/ml, respectively) (p<0.01)." (PMID 30011326, 2018). "The median serum CA9 concentration in cirrhosis patients was 482 pg/ml (range 11–1921)." (PMID 30011326, 2018). "CA9 levels were compared to stages of cirrhosis and HCC stages." (PMID 30011326, 2018). "HCC and cirrhosis patients were prospectively recruited and CA9 levels were determined." (PMID 30011326, 2018). "The CA9 levels in different stages of cirrhosis of HCC patients differed significantly between Child A, B and C patients, with the highest levels found in Child C stage patients (Child A median 228 pg/ml, Child B 810 pg/ml and Child C 930 pg/ml, respectively) (p<0.01)." (PMID 30011326, 2018). "The source of serum CA9, especially in cirrhosis, remains unclear and needs further investigation, especially because of the missing correlation of positive IHC and serum CA9 levels." (PMID 30011326, 2018). "Furthermore, in cirrhosis single hepatocytes showed positivity for CA9." (PMID 30011326, 2018). "Here we evaluated serum CA9 levels in HCC and cirrhosis patients." (PMID 30011326, 2018). "As CA9 levels showed a high correlation with stage of cirrhosis and was not an independent factor for survival, we evaluated 65 patients, matched according to stage of cirrhosis, without HCC." (PMID 30011326, 2018). "However, they found no CA9 expression in non-neoplastic tissue, which is interesting as patients with cirrhosis in our cohort had increased levels of CA9 as well and showed distinct positivity in ductular reactions." (PMID 30011326, 2018). "Furthermore, immunohistochemical CA9 expression in HCC and cirrhosis was evaluated." (PMID 30011326, 2018). "An evaluation of circulating CA9 in patients with HCC and patients with cirrhosis has not yet been done to our knowledge." (PMID 30011326, 2018). "However, patients with cirrhosis and without HCC also showed increased levels of CA9 which were comparable to cirrhotic patients with HCC." (PMID 30011326, 2018).
colitis (3 papers, 2021 to 2025). Inflammation of the colon. "Notably, vanillic acid was shown to restore intestinal epithelial homeostasis in DSS-induced colitis by inhibiting CA9/STIM1-mediated ferroptosis, thereby preventing epithelial cell death and preserving barrier integrity." (PMID 40699788, 2025). "Conversely, CA9 demonstrated resistance to ferroptosis under hypoxic conditions, and vanillic acid facilitated the binding of CA9 to STIM1, thereby inhibiting ferroptosis and alleviating colitis, which were consistent with the effects observed upon overexpression of CA9." (PMID 40417738, 2025).
colon adenocarcinoma (3 papers, 2022). "Overall, there data unveil a genetic interaction of CA9 with the tumor differentiation and lymphovascular invasion of colon adenocarcinoma." (PMID 35812185, 2022).
colorectal adenocarcinoma (3 papers, 2008 to 2021). The most common type of colorectal carcinoma. "In a previous study on the expression of hypoxia-related markers (HIF1α, HIF2α, CA9 and GLUT1) in colorectal adenocarcinomas, we found that in all tumours at least one of these proteins is immunohistochemically expressed." (PMID 18728663, 2008).
ependymoma (3 papers, 2020 to 2024). A WHO grade II, slow growing tumor of children and young adults, usually located intraventricularly. "We stained adjacent tissue sections for CA9, which is expressed by mesenchymal-like ependymoma tumor cells, IBA1, which is expressed by microglia, and GPNMB, which is expressed by DAM." (PMID 39561717, 2024). "We stained adjacent tissue sections for CA9, which is expressed by mesenchymal-like ependymoma tumor cells, IBA1, which is expressed by microglia, and GPNMB, which is expressed by DAM23." (PMID 36798206, 2024).
esophageal adenocarcinoma (3 papers, 2015 to 2018). A malignant tumor with glandular differentiation arising predominantly from Barrett mucosa in the lower third of the esophagus. "None of the clinicopathologic characteristics were significantly associated with intensity of CA9 expression in the esophageal adenocarcinoma group." (PMID 26156831, 2015). "High CA9 expression was significantly associated with high BMI1 expression in esophageal adenocarcinoma and precancerous lesions." (PMID 26156831, 2015). "High CA9 expression was significantly associated with cyclin E expression in esophageal adenocarcinoma and precancerous lesions." (PMID 26156831, 2015). "Our finding of the significant association of high CA9 expression with male sex implies that CA9 could be associated with men’s higher risk for esophageal adenocarcinoma." (PMID 26156831, 2015). "High CA9 expression was significantly associated with MCM4, MCM7 and Ki67 expression in esophageal adenocarcinoma and precancerous lesions." (PMID 26156831, 2015). "The median survival duration for patients with esophageal adenocarcinoma in the high CA9 expression group was 20 months, with a mean survival of 40 months." (PMID 26156831, 2015). "Its high expression in esophageal adenocarcinoma suggests that CA9 could be a therapeutic target in this cancer." (PMID 26156831, 2015). "High CA9 expression in esophageal adenocarcinoma suggests that CA9 could be a therapeutic target in this cancer." (PMID 26156831, 2015). "The reported expression of CA9 in esophageal adenocarcinoma has varied from 47 to 80 %." (PMID 26156831, 2015). "Finally, we analyzed the association of CA9 overexpression with BMI1, cyclin E, MCM4, MCM7 and Ki67 expression in esophageal adenocarcinoma." (PMID 26156831, 2015). "CA9 was not a significant prognostic marker in patients with esophageal adenocarcinoma but may be associated with men’s high risk for esophageal adenocarcinoma." (PMID 26156831, 2015). "Survival duration of esophageal adenocarcinoma did not significantly differ between patients with high CA9 expression and those with low expression." (PMID 26156831, 2015). "In esophageal adenocarcinoma and precancerous tissue groups, the patients with the high CA9 expression are 188 in male and 19 in female; the patients with the low or no CA9 expression are 89 in male and 29 in female." (PMID 26156831, 2015). "The reported percentages of expression of CA9 in esophageal adenocarcinoma vary, and CA9 expression in precancerous esophageal lesions has not been well studied." (PMID 26156831, 2015).
gastric tumor (3 papers, 2012 to 2023). "In addition, immunohistochemical expression of HIF-1α target genes (Glut1, VEGF, CA9, iNOS) is associated with gastric tumor progression." (PMID 22479608, 2012).
Hypertension (3 papers, 2009 to 2025). The presence of chronic increased pressure in the systemic arterial system. "Hypertension predicted better outcome among both grade 3 and GBM patients, whereas high CA9 and low VEGF were associated with poorer progression-free survival (PFS) among those with GBM." (PMID 19920819, 2009).
medulloblastoma (3 papers, 2010 to 2020). A malignant, invasive embryonal neoplasm arising from the cerebellum. "In medulloblastoma, tumours with increased expression of VEGF, GLUT1 or CA9, markers indicative of tumour hypoxia, result in reduced overall patient survival." (PMID 30943920, 2019).
metastatic colorectal cancer (3 papers, 2009 to 2019). "The purpose of this comparative analysis was to evaluate whether CA9 and VEGF expression are associated with survival outcomes in patients with metastatic colorectal cancer (mCRC) after treatment with bevacizumab as second or later line treatment." (PMID 19619339, 2009).
Oral leukoplakia (3 papers, 2018 to 2021). A thickened white patch on the oral mucosa that cannot be rubbed off. "The present work addresses the determination of CA9 in oral leukoplakia by quantitative PCR in blood and tissues as a diagnostic and prognostic method for better management of patients with said disease." (PMID 29745265, 2018). "CA9 was also expressed significantly in malignant oral disorders (mostly oral leukoplakia), which contributes to individualized prediction." (PMID 33815132, 2021). "Another study in OSCC described the effect of CA9 mRNA, but it was isolated and measured out of the peripheral blood of patients with oral leukoplakia." (PMID 30654595, 2019). "OSCC and leukoplakia tissue samples and healthy tissue samples were selected to determine the CA9 expression levels in these circumstances." (PMID 29745265, 2018). "The presence of CA9 was detected in all samples from tumour tissues and leukoplakias and in both the HeLa positive control included in the study and the patient samples." (PMID 29745265, 2018). "The objective of this study was to evaluate the possibility of detecting the level of CA9 expression in the blood of patients with leukoplakia by means of quantitative real-time PCR for use as a biomarker." (PMID 29745265, 2018). "For a patient with leukoplakia, a tissue sample and a blood sample were available; in this case, the expression of CA9 was detected in the tissue sample with leukoplakia but not in the blood samples." (PMID 29745265, 2018). "The follow-up performed allowed us to determine that this case later became malignant with the development of a OSCC; however, the CA9 expression level was not higher than in the other leukoplakias." (PMID 29745265, 2018).
paraganglioma (3 papers, 2018 to 2024). A benign or malignant neoplasm arising from paraganglia located along the sympathetic or parasympathetic nerves. "Analysis of paraganglioma and pheochromocytoma samples revealed a substantial correlation of PD-L2 expression with carbonic anhydrase 9 (CAIX) and hypoxia-driven HIF-1α, which was not the case with PD-L1 expression." (PMID 38165484, 2024). "According to the study of a large number of malignant primary tumor tissues from pheochromocytomas and paragangliomas, PD-L2 expression but not PD-L1 expression is significantly associated with stronger hypoxia-driven HIF-1α and carbonic anhydrase 9 (CAIX)." (PMID 30061885, 2018). "According to the analysis of samples from paragangliomas and pheochromocytomas, PD-L2 expression but not PD-L1 expression is significantly correlated with strong hypoxia-driven HIF-1α and carbonic anhydrase 9 (CAIX)." (PMID 33422072, 2021).
thyroid tumor (3 papers, 2010 to 2025). A benign or malignant neoplasm affecting the thyroid gland. "Significantly, loss of NOX4 in human papillary thyroid cancer cells decreases HIF1α targeting genes such as SLC2A1 and CA9, highlighting the potential importance of NOX4-mediated metabolic reprogramming in thyroid tumor." (PMID 30367082, 2018).